MIR6884 (microRNA 6884)
Synonyms: hsa-mir-6884
Gene: MicroRNA gene on chromosome 17 (40,026,332 to 40,026,409, reverse strand). Ensembl gene ENSG00000283721.
Homologues: Orthologues: chimpanzee MIR6884 (100% identical).